APOB (apolipoprotein B)
Diseases named in the same sentence as APOB in open-access papers (continued):
Sharing a sentence is not in itself a finding about the gene and the disease.
Obesity (continued). "Significant placebo-adjusted decreases from baseline in blood pressure, low-density lipoprotein (LDL) cholesterol, triglycerides, ApoB, ApoC3, and hsCRP were observed following orforglipron treatment in participants with T2D and/or overweight or obesity." (PMID 40481478, 2025). "An interesting observation is that, in univariate MR analysis, an increase in obesity-related indicators significantly elevates the ApoB/ApoA1 ratio." (PMID 38310324, 2024). "In order to highlight the significant pleiotropic effects of APOB activation, our study links two metabolic co-morbidities of EC (obesity and T2D)." (PMID 39193372, 2024). "HDL increased (p < 0.05), and ApoB (p < 0.05) decreased in the morbid obesity and obesity subgroups, while TG decreased in the morbid obesity group (p < 0.05)." (PMID 39339733, 2024). "The concentrations of triglycerides and ApoB were significantly higher, while the ApoA1 concentrations were significantly lower in individuals with obesity than those with overweight and normal BMI in both assessments." (PMID 39203787, 2024). "As for the lipid profile, in our study, changes in resistin concentrations correlated positively with ApoB concentrations in subjects with obesity." (PMID 39519480, 2024). "Obesity increases fatty acid release from adipose tissue, resulting in higher very-low-density lipoprotein, TG and apolipoprotein B (apoB) secretion." (PMID 36980222, 2023). "Elevated ApoB and obesity prevalence were lower for tree nut consumers across race and ethnic groups." (PMID 37869524, 2023). "The genomic loci rendering resistance to obesity in macaques chronically consuming HFD were identified, and are as follows: three single-nucleotide polymorphisms—two in apolipoprotein B (APOB) and one in phospholipase A2 (PLA2G4A)." (PMID 36984693, 2023). "At baseline, there were statistically significant differences in WC, BMI, and prevalence of obesity among the groups, with the highest values in the high-apoB groups." (PMID 35462864, 2022). "There are few studies associating apolipoprotein B concentrations with BMD, and there is some debate about the association between obesity and BMD." (PMID 36568987, 2022). "Our finding showed that the association between impaired anti-inflammatory function of apoB-depleted plasma and NAFLD was attenuated but remained significant after adjustment for the obesity indices." (PMID 35413066, 2022). "It suggests that the effects of NAFLD on the anti-inflammatory functionality of apoB-depleted plasma cannot be entirely explained by the obesity and involvement of additional NAFLD-specific mechanisms seem likely." (PMID 35413066, 2022). "HDL anti-inflammatory capacity values of apoB-depleted plasma were also positively correlated with obesity indices including Log visceral fat, BMI, WC, and Log WHR." (PMID 35413066, 2022). "Studies found that the trends of apoB and LDL-C differs in more than one quarter of people, especially in people with metabolic risk factors (such as obesity or type 2 diabetes) and those taking statins." (PMID 35573992, 2022). "Participants in the high-apoB tertile had higher WC, BMI, and prevalence of obesity than those in the low- and middle-apoB tertiles." (PMID 35462864, 2022). "Elevated obesity (weight overload) leads to elevated levels of apolipoprotein B in the blood, which decrease with exercise, vegetarianism, and hypolipidemia." (PMID 36568987, 2022). "The impairment of the anti-inflammatory function of apoB-depleted plasma was related to obesity and NAFLD markers." (PMID 35413066, 2022). "We also observed a significant correlation between impaired anti-inflammatory capacity of apoB-depleted plasma and obesity indices namely BMI, WHR, WC, and visceral fat." (PMID 35413066, 2022). "The ApoB EcoRI polymorphism was found to have a significant relationship with serum HDL-C levels and obesity indices in the current work." (PMID 35732646, 2022).
Obesity (continued). "Impaired anti-inflammatory capacity of apoB-depleted plasma was correlated with fatty liver and obesity indices." (PMID 35413066, 2022). "The APOB-rs1042031 was the most relevant gene marker related to glucose and lipid metabolism profiles, as well as with clinical obesity and periodontitis." (PMID 34805411, 2021). "The APOB-rs1042031 was the most relevant gene marker related to glucose and lipid metabolism profiles, as well as with obesity and periodontitis." (PMID 34805411, 2021). "ApoB regulates the secretion of very low-density lipoprotein, which is present at high circulating concentrations in patients with obesity, T2DM, and hypertriglyceridemia." (PMID 34034748, 2021). "For example, adolescent girls with obesity and polycystic ovary syndrome have increased fasting and postprandial plasma triglycerides and ApoB-lipoprotein remnants, and these indices are highly associated with early subclinical CVD risk." (PMID 33910581, 2021). "A number of literatures have revealed that obesity increases the ApoB /ApoA1 ratio and that ApoA1 levels were positively associated with the risk of metabolically healthy obesity (MHO), but the ApoB /ApoA1 ratio is negatively associated." (PMID 34930329, 2021). "The degree of LFC had a positive correlation with total cholesterol, triglyceride, ApoB, and ApoE in patients with overweight/obesity and type 2 diabetes." (PMID 34899591, 2021). "The currently reported anti-obesity mechanisms of COS mainly include inhibition of apolipoprotein B (ApoB) levels, PPAR-γ, bile acid secretion, pancreatic lipase production and reduction of serum ghrelin concomitant with increasing leptin." (PMID 34660667, 2021). "The manuscript aimed to evaluate the influence of lipids multiple genetic variants (APOA and APOB) on insulin resistance and MetS in OSA patients using obesity as a confounding factor." (PMID 33005209, 2020). "Female gender, older age and obesity were all consistently associated with higher LDL-C and apoB levels, as previously reported in ecological studies." (PMID 31809516, 2019). "It was reported that, among other parameters (BMI, waist circumference, and apolipoprotein-B), MHO subjects showed lower TG : HDL-C ratio compared to those affected by obesity with cardiometabolic risk." (PMID 31885562, 2019). "Polymorphisms of the APOB, APOE, ADIPOQ, PLIN4, and HSD11β1 genes are important examples of genetic causes associated with dyslipidemias and obesity." (PMID 30507998, 2018). "A study with follow-up to age twenty found higher overweight and obesity rates as well as higher concentrations of total and low-density lipoprotein cholesterol, leptin and apolipoprotein B in those born by CS29." (PMID 30310162, 2018). "Many reports attribute more weight to the ApoB/ApoA1 ratio as an index of cardiovascular risk and it is considered as an effective predictor of CAD risk in overweight and obesity." (PMID 29544473, 2018). "In a Drosophila genetic screen, we discovered that when haplo-insufficient, microsomal triglyceride transfer protein (mtp), required for the biosynthesis of apoB-lipoproteins, suppressed the development of diet-induced obesity." (PMID 28095410, 2017). "PCSK9 (TG, HDL cholesterol, ApoB and ApoA1/ApoB) was shown interactions with overweight/obesity to influence serum lipid levels." (PMID 26744084, 2016). "Among of the five PC metabolites associated with obesity and T2D based on FTO genotype, four (PC aa C36:5, C38:5, C38:6, and C40:6) are associated with apolipoprotein B (ApoB)." (PMID 27249024, 2016). "With the aim to show that APOB mRNA editing is a target mechanism for fighting against obesity, we searched to modulate APOBEC1 enzymatic activity in vivo in the rabbit species by modulating APOBEC1 gene expression through transgenesis." (PMID 25216115, 2014).
Obesity (continued). "Low grade inflammation is associated with obesity as well as with CVD and thus it is possible that associations of 25OHD with triglyceride concentration and apoB/apoA ratio relate to the known connection of vitamin D with inflammation." (PMID 25000408, 2014). "In the search of new targets for obesity, we have investigated the APOB mRNA editing protein (APOBEC1) gene pathway that is involved in fat absorption in the intestine." (PMID 25216115, 2014). "In the overweight and obesity group, the area under ROC curve (AUC) was the highest for apoB/apoA1 (0.655)." (PMID 23554700, 2011). "Total and LDL-C, TG, FBG and apoB levels and total/HDL-C ratio, apoB/apoA ratio, and insulin resistance showed a significant correlation with all the three obesity indices." (PMID 21261206, 2010). "In addition to the management of LDL-C, the treatment of atherogenic dyslipidemia, defined by elevated levels of triglycerides and apolipoprotein B, has garnered attention due to the increasing prevalence of obesity and insulin resistance." (PMID 40943795, 2025). "We conducted two-step MR analysis to explore whether the effect of TG, LDL-C and ApoB on TL was mediated via obesity-related phenotypes, i.e., BMI, BFP, WHR, HC and WC." (PMID 38863926, 2024). "However, after reverse MR analysis, the elevation of the ApoB/ApoA1 ratio seems to be correlated with the decrease in obesity-related indicators." (PMID 38310324, 2024). "The typical lipid abnormalities associated with obesity include elevated levels of TGs, very low-density lipoprotein (VLDL), and apolipoprotein B (Apo B), while HDL and apolipoprotein A-I (Apo A-I) levels are generally low, and LDL levels are usually normal or slightly elevated." (PMID 39338234, 2024). "The mediation effect of TG, LDL-C and ApoB on TL via obesity-related phenotypes." (PMID 38863926, 2024). "This study also showed that TG and ApoB levels showed a trend towards an increase with BMI and that ApoAI, TG/HDL-C, and ApoB/ApoA ratios were linked to certain features of PCOS, specifically insulin resistance and obesity." (PMID 36980195, 2023). "Apolipoprotein A1 and apolipoprotein B differences are affected by obesity." (PMID 36010152, 2022). "Further research indicated that reduced serum APOB was closely related to inflammation and increased serum APOB may be the key therapeutic target to reduce obesity-related inflammation." (PMID 35688870, 2022). "Using the integrated strategy of network pharmacology and greedy algorithms, the important roles of some targets IL6, HMCGR, PPARA, and APOB for management of hyperlipidemia and obesity were highlighted in this work, which was also in accord with the previous publications." (PMID 35586687, 2022). "However, in rodents, apolipoprotein B is important in reducing liver lipid accumulation during the progression of obesity." (PMID 34305631, 2021). "As abnormal lipid metabolism promotes pancreatic tumorigenesis and obesity is an important risk factor for the PDAC7, rs183117027 variant may affect the development of PDAC by disturbing the lipid metabolic function of APOB." (PMID 30206226, 2018). "Despite the size and detail of data in AMORIS, we only found a modest positive association between serum levels of glucose, apoB/ApoA-1 and BC severity, suggesting that these factors are not the main players in linking obesity and BC aggressiveness." (PMID 28376727, 2017). "Hence, our results indicate that increased expression of vigilin enhances apoB synthesis in conditions of lipid availability (i.e., in obesity) to further promote VLDL secretion." (PMID 27665711, 2016). "Taken together, our findings alongside the current collective literature suggests that APOB is a primary determinant of high fat diet induced obesity, and may render multigenerational impact through a maternal parent of origin effect." (PMID 27811965, 2016). "Analysis did not reveal a positive association between the apoB XbaI gene polymorphism (X) and obesity-related phenotypes." (PMID 25889118, 2015).
Obesity (continued). "We have examined the genotypic and allelic frequencies and the effect of apoB XbaI polymorphism (X) on obesity and lipid profile in well-defined Egyptian obese and non-obese populations." (PMID 25889118, 2015). "Furthermore, the odds of obesity were 1.35 times as high for a person with an apoB level of 1.00 g/L as for a person with a level of 0.80 g/L." (PMID 21159217, 2011). "Likewise, to control more fully for obesity, the model on apoB was further adjusted for waist-to-hip ratio." (PMID 20396381, 2010). "The obesity-induced increase in cardiac triglycerides was abolished in human apoB-transgenic mice." (PMID 19390571, 2009). "Interestingly, overexpression of apoB in the heart of long-term-fat-fed obese mice not only prevented cardiac triglyceride accumulation but also reduced the effect of fat-feeding and obesity on genes controlling fatty acid metabolism in the heart." (PMID 19390571, 2009). "We fed the fat-enriched diet to human apoB-transgenic male mice and litter-mate C57Bl/6 controls for ∼1 year to explore the impact of increased rates of cardiac lipoprotein formation in the setting of obesity and increased cardiac triglyceride stores." (PMID 19390571, 2009). "Therefore, ApoB can be considered a potential therapeutic target for obesity." (PMID 37047284, 2023). "Indeed, in a Caucasian father-son pair with NAFLD, obesity and low LDL cholesterol, both had a heterozygous mutation in APOB gene (c.1830-1G > A) which is a pathogenic splicing variant which causes truncated ApoB thus resulting in FHBL and they were heterozygous also for the PNPLA3 rs738409." (PMID 34829753, 2021). "Furthermore, smoking and obesity were associated with significantly higher levels of apoB, but not with significantly higher LDLc levels." (PMID 30298424, 2019). "Consequently this study and analysis were done to examine association of obesity with apoB, apoA-I, and apoC-III content of both non-HDL and HDL." (PMID 28473926, 2017). "In addition, several observations suggested that the role of cysteine in hepatic synthesis of ApoB may explain the epidemiology link of tCys and obesity." (PMID 21838883, 2011). "FBS: fasting blood sugar, FH: family history, TG: triglycerides, HDL: high-density lipoproteins, Tchol: total cholesterol, LDL: low-density lipoproteins, ApoA1: apolipoprotein A1, ApoB: apolipoprotein B, FTO: fat mass and obesity." (PMID 39925495, 2025). "In the present study, we analyzed the effects of human HSPB1 on obesity-related complications and comorbidities by crossing a human HSPB1-overexpressing strain with a mouse model of MetS overexpressing human APOB-100." (PMID 40855499, 2025). "Lipid abnormalities including elevated triglyceride, very-low-density lipoprotein, apolipoprotein B, LDL-cholesterol levels, low HDL-cholesterol, and apolipoprotein A-I levels are commonly observed in patients with obesity." (PMID 39081789, 2024). "In our study, subjects with obesity had higher concentrations of LDL, TG, and ApoB, and lower concentrations of HDL and ApoA1 in both assessments compared to subjects with overweight and normal BMI." (PMID 39203787, 2024). "This triggered a new round of molecular studies linking the biochemical background (apoprotein(a), apoB, LDL-C, triglyceride level), environmental and acquired factors (smoking, obesity) and genetic factors." (PMID 39057646, 2024). "Variables belonging to the inflammatory and obesity clusters predicted high ferritin values while the proatherogenic cluster factors (positive loadings of TC, LDL-C, apoB and TG) predicted high sTfR values." (PMID 36670881, 2022). "This study identifies murine double minute 2 (MDM2) as a novel E3 ubiquitin ligase that targets apolipoprotein B (ApoB) for proteasomal degradation, leading to impaired TG‐VLDL secretion and hepatic TG accumulation in obesity." (PMID 35524581, 2022).
Obesity (continued). "Therefore, it is essential to investigate new biomarkers of bone health, such as serum apolipoprotein B. In previous studies, obesity lead to an increase in bone mineral density because of the higher mechanical load, which may contribute in protecting the bone." (PMID 36568987, 2022). "In overweight or obesity MAFLD patients, total cholesterol, LDL-c, ApoB, ApoE, and Lp(a) achieved AUCs of 0.679, 0.677, 0.689, 0.684, and 0.674, respectively (all p < 0.02)." (PMID 34899591, 2021). "In those with overweight/obesity, there were dose–response relationships between moderate-to-severe steatosis and total cholesterol, triglyceride, HDL-c, LDL-c, ApoB, ApoE, and Lp(a)." (PMID 34899591, 2021). "In their study, the positive associations between FT and FAI and the ApoB/ApoA1 ratio were no longer significant after adjusting for age and BMI together, which indicated that obesity might make more of a contribution to the increased ApoB/ApoA1 ratio than FT and FAI in adult PCOS patients." (PMID 35069437, 2021). "In subjects with obesity WBC, PLT, folic acid, AST, ALT, γ-GT, LDL, ApoB, HbA1c, and T3 concentrations decreased significantly at the end of the study." (PMID 34444842, 2021). "In MAFLD patients with overweight/obesity, there were dose–response relationships between moderate-to-severe steatosis and total cholesterol, triglyceride, HDL-c, LDL-c, ApoB, ApoE, and Lp(a) (all p for trend <0.05)." (PMID 34899591, 2021). "Adolescent girls with obesity and PCOS were found to have elevated fasting and postprandial plasma TG and ApoB-lipoprotein remnants." (PMID 32366216, 2020). "Production of lipoproteins in the heart is mediated by apoB and MTP and unregulated by myocardial MTP following fasting and high-fat diet-induced obesity." (PMID 29530023, 2018). "Thus, in spite of the size and great detail of the data in AMORIS, we only found a modest positive association between serum levels of glucose, apoB/ApoA-1 and BC severity, suggesting that these factors are not the main players in the link between obesity and BC aggressiveness." (PMID 28376727, 2017). "A study of adolescent PCOS in our hospital confirmed that APOB/APOA1 is a good predictor of MS and that the ratio was higher in women with PCOS with obesity and a high free androgen index." (PMID 27902723, 2016). "Altogether, the apoB/apoA ratio has been shown to be in a linear association with cardiovascular risk factors in diverse groups, and our findings indicate that this association can be generalized to obesity indices, irrespective of the strength of the association." (PMID 21261206, 2010). "Body mass index (BMI SDS) was inversely correlated with HDL-C (p < 0.001), and obesity (BMI z-score > 2 SDS) was associated with lower HDL-C and higher LDL-C, non-HDL-C, and ApoB." (PMID 41898801, 2026). "BMI: body mass index, BP: blood pressure, FBS: fasting blood sugar, Tchol: total cholesterol, TG: triglycerides, HDL: high-density lipoproteins, LDL: low-density lipoproteins, ApoA1: apolipoprotein A1, ApoB: apolipoprotein B, FH: family history, FTO: fat mass and obesity." (PMID 39925495, 2025). "Higher tertiles of LDLC, TC, TG, ApoB and ApoB: ApoA1, along with the lowest tertiles of HDLC and ApoA1 exhibited higher prevalence of Type II diabetes mellitus (all p ≤ 0.024) and overweight or obesity (all except for TC, p ≤ 0.024)." (PMID 40375303, 2025). "βGluCnCs intake for 12 weeks significantly increased the average change in the ApoA1/ApoB ratio in subjects with overweight and low-LDLc levels, but not in those with obesity and high-LDLc levels." (PMID 39408385, 2024). "In addition, increased levels of APOB were found in plasma and VAT from patients with obesity compared to normoweight individuals revealing it concerning and important role in cardiometabolic health outcomes of patients with obesity." (PMID 38703299, 2024).